PIGH (phosphatidylinositol glycan anchor biosynthesis class H)
Description:
Part of the glycosylphosphatidylinositol-N-acetylglucosaminyltransferase (GPI-GnT) complex that catalyzes the transfer of N-acetylglucosamine from UDP-N-acetylglucosamine to phosphatidylinositol and participates in the first step of GPI biosynthesis.
Synonyms: GPI-H
Tractability: PROTAC: ubiquitination databases record sites on it.
Gene: Protein-coding gene on chromosome 14 (67,581,955 to 67,600,286, reverse strand). Ensembl gene ENSG00000100564.
Subcellular location: Endoplasmic reticulum membrane
Pathways (Reactome):
Metabolism of proteins: Synthesis of glycosylphosphatidylinositol (GPI)
Gene Ontology:
Molecular function: protein binding
Biological process: GPI anchor biosynthetic process
Cellular component: endoplasmic reticulum membrane; glycosylphosphatidylinositol-N-acetylglucosaminyltransferase (GPI-GnT) complex; endoplasmic reticulum
Genetic constraint (gnomAD): Loss-of-function variants: 9 observed, 8.22 expected, observed/expected ratio (o/e) 1.09, 90% interval 0.65 to 1.78. That is too few expected variants to judge how well the gene tolerates losing a copy. Missense variants: 157 observed, 167.25 expected, observed/expected ratio (o/e) 0.94, 90% interval 0.82 to 1.07. Synonymous variants: 58 observed, 62.68 expected, observed/expected ratio (o/e) 0.93, 90% interval 0.75 to 1.15.
Gene-disease validity (ClinGen):
ClinGen rates the evidence that PIGH causes each of these diseases.
glycosylphosphatidylinositol biosynthesis defect 17 (autosomal recessive): Limited.
Homologues: Orthologues: chimpanzee PIGH (100% identical), dog PIGH (97% identical), guinea pig PIGH (89% identical), macaque PIGH (88% identical), mouse Pigh (88% identical), pig PIGH (82% identical), rabbit PIGH (82% identical), rat Pigh (81% identical), tropical clawed frog pigh (60% identical), zebrafish pigh (54% identical).
Diseases named in the same sentence as PIGH in open-access papers:
PIGH is named in the same sentence as 11 diseases in open-access papers, as found by Europe PMC text mining. Sharing a sentence is not in itself a finding about the gene and the disease. The quoted sentences say what the papers report.
arthrogryposis (2 papers, 2015 to 2018). A rare, non-progressive congenital disorder characterized by multiple joint contractures which are present at birth. "Although a PIGH splicing variant in Belgian Blue cattle has been shown to result in arthrogryposis, the consequences of PIGH mutations in humans have not yet been described." (PMID 29573052, 2018). "We herein describe the identification of an intronic mutation that disrupts PIGH function by causing the skipping of exon 2, thereby causing a severe and lethal form of arthrogryposis in homozygous animals." (PMID 25895751, 2015). "The resulting PIGH protein is likely to be non-functional as it lacks essential domains, and hence to cause arthrogryposis." (PMID 25895751, 2015).
developmental delay (2 papers, 2018 to 2021). "PIGH deficiency is a newly described and rare disorder associated with developmental delay, seizures and behavioral difficulties." (PMID 33156547, 2021).
epilepsy (1 paper, 2018). A brain disorder characterized by episodes of abnormally increased neuronal discharge resulting in transient episodes of sensory or motor neurological dysfunction, or psychic dysfunction. "Scanning exomes from 7,833 parent–child trios and 1,792 singletons from the DDD study for biallelic variants in this gene‐set uncovered a rare PIGH variant in a boy with epilepsy, microcephaly, and behavioral difficulties." (PMID 29573052, 2018).
glioblastoma (1 paper, 2023). The most malignant astrocytic tumor (WHO grade IV). "From this analysis, we found ten DEGs specific to IDH1-wt glioblastoma, namely, S100A11, AC091932.2, PIGH, AC020910.5, RPS8P6, AC105339.6, AL589986.1, AL049874.3, CEBPD, and Z99496.1." (PMID 37568598, 2023).
virus infection (1 paper, 2025). "The successful knockout of PIGC and PIGH was confirmed by impaired Echo7 virus infection and sequencing of the targeted genomic loci." (PMID 41252368, 2025).
tumor (2 papers, 2017 to 2025). "Notably, there was a significant positive association between KIF21A and PIGH with activated NK cells, which are immune cells with broad-spectrum anti-tumor effects, while RPS6KA2 was negatively correlated with its activation." (PMID 40098701, 2025).
cancer (1 paper, 2025). A tumor composed of atypical neoplastic, often pleomorphic cells that invade other tissues. "Downregulation of PIGH expression leads to heightened chemotherapy resistance and bolsters the phenomenon of immune escape within the realm of cancer." (PMID 40098701, 2025).
infection (1 paper, 2025). The state of being infected such as from the introduction of a foreign agent such as serum, vaccine, antigenic substance or organism. "We also found that PIGT-, PIGH- or GPAA1-KO cells did not support Echo7 infection." (PMID 41252368, 2025).
PIGH also shares sentences with these, for which no sentence is quoted: breast carcinoma (1 paper); lung carcinoma (1); microcephaly (1).